LSP1 (lymphocyte specific protein 1)
Diseases named in the same sentence as LSP1 in open-access papers (continued):
Sharing a sentence is not in itself a finding about the gene and the disease.
tumor (continued). "The gene LSP1, on the other hand, plays an important part in transendothelial migration of tumor cells in the bloodstream and thus helps in cancer development." (PMID 17207284, 2007). "Expressions of the remaining three genes (NAB2, EHD1 and LSP1) are either upregulated or downregulated in the various tumors and also in SRBCTs depending on the tumor subgroups." (PMID 17207284, 2007). "Human and mouse tumors differed from normal embryonic colon by their loss of expression modules enriched for tumor suppressors (EDNRB, HSPE, KIT and LSP1)." (PMID 17615082, 2007). "Meanwhile, there are studies contradicting the concept of LSP1 as a tumour suppressor." (PMID 40038352, 2025). "Overexpression of LSP1 partially reversed the tumor suppressive effect of FCGR1A downregulation." (PMID 38879666, 2024). "Moreover, cell type-specific detection of LSP1 in BrCa tumor specimens revealed that LSP1 expression is predominantly restricted to infiltrating leukocytes and was significantly correlated with better outcome." (PMID 37664640, 2023). "Proto-oncogenes are those genes that are involved in cell growth and proliferation, with potential examples including the ATM, FGFR2, FN1, IGF1, MAP3K, MMP7, and RHOC genes, while the CASP8 and LSP1 genes have been reported to possess tumor-suppressive properties in certain types of cancer." (PMID 33112566, 2020). "LSP1 expression was increased in tumor-infiltrating T cells and could be induced by T cell receptor activation." (PMID 33020243, 2020). "Moreover, tumor volume and weight in Lsp1 KO mice were lower than in WT mice as determined on day 14 after tumor inoculation." (PMID 33020243, 2020). "In the tumor, however, they were significantly higher in the infiltrated CD4+ and CD8+ T cells of Lsp1 KO mice than in those of WT mice, suggesting that Lsp1 deficiency increases antitumor immunity by inducing TNF-α+ and IFN-γ+ expression in tumor-infiltrating T cells." (PMID 33020243, 2020). "Given that the release of tumor-associated neoantigens occurs in the TME via the cancer-immunity cycle, the released tumor antigens could activate tumor-infiltrating T cells to upregulate LSP1 expression." (PMID 33020243, 2020). "We next questioned whether LSP1 regulation of tumor growth originates entirely from its effect on T cell migration." (PMID 33020243, 2020). "Additionally, we investigated the LSP1 expression level in benign tissue around LSP1 high tumor by IHC." (PMID 32003759, 2020). "LSP1 expression was elevated in tumor-infiltrating T cells and could be induced by the stimulation of T cells with TCR and IFN-γ." (PMID 33020243, 2020). "The data of immunofluorescence colocalization showed that there were a few cells in GBM samples with co-staining of LSP1 and glial fibrillary acidic protein (GFAP), which may imply a tumor cell-related LSP1 expression in GBM." (PMID 32003759, 2020). "Since these immunosuppressive cells lead to cytotoxicity CD8+ T cells “exhaustion”, LSP1 expression in these cell subpopulations may contribute to the “cold tumor” status of GBM." (PMID 32003759, 2020). "We found that Lsp1 KO mice had significant reductions in tumor growth as compared with WT mice." (PMID 33020243, 2020). "It was not clear whether the reduction of tumor growth in Lsp1 KO mice stemmed from the increased infiltration of only CD8+ T cells in tumor tissue, since the frequency of CD11b+Ly6ClowF4/80high TAMs was also substantially decreased in the tumors of Lsp1 KO mice." (PMID 33020243, 2020). "Thus, we proposed that LSP1 mainly functioned with non-tumor cell population in GBM." (PMID 32003759, 2020). "Taken together, elevated LSP1 expression levels induced by tumor-associated antigens or IFN-γ may hamper further migration of tumor-infiltrating T cells inside the tumor mass, resulting in establishment of the ‘infiltrated-excluded’ tumor phenotype." (PMID 33020243, 2020). "Thus, LSP1 regulation is tumor class specific and useful for subcategorization of tumors." (PMID 17207284, 2007).
tumor (continued). "The results showed that IL2RA, DNMT3B, ADRM1, and NRIP1 were highly expressed in tumor tissue compared to normal tissue, while ALDH2, NYNRIN, LSP1, and CALCRL were the opposite." (PMID 38322112, 2024). "The results showed that the expression levels of LSP1 in THP1(M0), M1 and M2 macrophages induced from THP1 cells, and PBMC were significantly higher than that in tumor cells." (PMID 32003759, 2020). "The results showed that the frequencies of tumor-infiltrating CD3+ and CD4+ T cells were similar between WT and Lsp1 Tg mice." (PMID 33020243, 2020). "Furthermore, expression of four proteins is associated with tumor progression/high risk AML: DOT1L, mTOR, VIM and ZNF521, whereas the expression of six proteins is associated with tumor suppression/low risk AML: AEBP2, CAST, CBFB, LSP1, MAP1S and probably PCBP1." (PMID 30634713, 2019). "Tocilizumab may control cytokine release syndrome in the context of immunotherapy.JBH492 may affect the biological behavior of SKCM cells or the tumor microenvironment by targeting and regulating genes such as CD8A and LSP1." (PMID 40547036, 2025). "LSP1 exhibited a negative correlation with tumor purity but demonstrated a positive correlation with the infiltration levels of various immune cells, including B cells, CD8+ T cells, CD4+ T cells, neutrophils, and dendritic cells." (PMID 40038352, 2025). "Meanwhile, LSP1 was negatively correlated with tumour purity, which suggested that it was primarily expressed in infiltrating immune cells, not tumour cells." (PMID 40038352, 2025). "Indeed, expression of IFN-γ and TNF-α was increased in tumor-infiltrating CD4+ and CD8+ T cells of Lsp1 KO mice, while it was markedly reduced in those of Lsp1 Tg mice." (PMID 33020243, 2020).
cancer (15 papers, 2007 to 2026). A tumor composed of atypical neoplastic, often pleomorphic cells that invade other tissues. "Down-regulation of LSP1 has been shown in several cancers and its over-expression is associated with cell apoptosis." (PMID 32321427, 2020). "Several SNPs in LSP1 and H19 were most likely associated with the risk of developing cancer." (PMID 26770289, 2016). "The underlying biological mechanism through which LSP1 may influence cancer development remains to be elucidated." (PMID 24681604, 2014). "There is some evidence to place the role of LSP1 in solid tumours, either driving or inhibiting cancer progression." (PMID 40038352, 2025). "Five genes were implicated in the development of other cancer types: SRGAP2C, MAP3K1, FGFR2, LSP1, and FMNL3." (PMID 36703164, 2023). "Leukocyte-specific protein 1 (LSP1) is known as an endothelial gatekeeper because it controls endothelial permeability and transendothelial cell migration, including that of leukocytes and potentially metastatic cancer cells." (PMID 41596753, 2026). "Additionally, the genes SRGAP2C, LSP1, and FMNL3 have been implicated in the etiology of other types of cancer." (PMID 36703164, 2023). "However, the expression pattern of LSP1 and its role in cancer biology and the regulation of the TME remain to be further explained." (PMID 32003759, 2020). "Among them, leukocyte-specific protein 1 (LSP1) was the only one whose abundance was significantly associated with HPV16 infection (group B vs A, FC = 0.49), but not with cancer status (group C vs B, FC = 1.03)." (PMID 40038352, 2025).
infection (5 papers, 2007 to 2025). The state of being infected such as from the introduction of a foreign agent such as serum, vaccine, antigenic substance or organism. "The monogenic recessive locus conferring suppressed leaf infectivity and cell-to-cell movement in B149 is allelic to two mutant alleles of lsp1 (lsp1-1 and lsp 1-2) obtained by a positive selection scheme based on the loss of phenotype after infection with TuMV." (PMID 17912362, 2007). "We found collectively among SP-A variants several genes such as AKT1, BTK, CCL9, PPARG, and RELA to exhibit higher expression in females, whereas, CFLAR, C1QC, LSP1, CKAP2, KAT2B, TACC2, and RCC2 exhibited higher expression in males after infection." (PMID 32670284, 2020). "However, in response to infection, male mice exhibited higher expression levels of CFLAR, and FKBP5 (KO, 1A3), AKT1, and CCL9 (1A3, 6A2), C1QC (6A2), LSP1 (1A3, 6A2, and 6A4), CKAP2, and KAT2B (KO), TACC2 (1A0), RCC2 (1A3, 6A2), PPARG (1A3, 6A4), and ERP44 (6A2) compared to females." (PMID 32670284, 2020). "The female mice exhibited higher expression levels of AKT1, BTK, CCL9, and LSP1 (KO, 1A0), PPARG (KO, 1A0, and 6A2), CFLAR, and ERP44 (1A0, 6A4), CCL9 (KO, 1A0, and 6A4), RCC2, and RELA (KO), KAT2B (6A2) and FKBP5 (1A0, 6A2, and 6A4) compared to males in response to infection." (PMID 32670284, 2020). "Whilst infection does not alter BM MK cell numbers or in vitro MK lineage bias, it does reduce circulating TPO, lead to smaller MK size, and a bias towards lower ploidy cells with increased LSP-1+ expression." (PMID 41296814, 2025).
intestinal diseases (1 paper, 2022). "Differential alternative splicing (AS) genes, such as Myo9b, Lsp1, and Git2, have major functions in intestinal diseases." (PMID 35496266, 2022).
LSP1 also shares sentences with these, for which no sentence is quoted: lymphoma (6 papers); Hodgkin’s disease (3); breast invasive carcinoma (2); ischemic stroke (2); Arthritis (1); atrial fibrillation (1); breast tumors (1); Cerebral ischemia (1); chronic obstructive pulmonary disease (1); Crohn disease (1); Epstein-Barr virus infection (1); gastrointestinal stromal tumor (1); Hyperglycemia (1); Hyperinsulinemia (1); interstitial lung disease (1); lymphopenia (1); mesothelioma (1); metabolic disorders (1); Obesity (1); prostate carcinoma (1); renal cell carcinoma (1); sarcoma (1); Sepsis (1); teratospermia (1); type 2 diabetes (1); type 2 diabetes mellitus (1); ulcerative colitis (1).